CD4 (CD4 molecule)
Diseases named in the same sentence as CD4 in open-access papers (continued):
Sharing a sentence is not in itself a finding about the gene and the disease.
Immunodeficiency (continued). "In humans, CD4+ T-cell-dependent immune deficiency has also been shown to be associated with fatal disseminated T. marneffei infections in HIV-positive patients, as well as a reduction in lymphocyte numbers and function in HIV-negative patients with T. marneffei infections." (PMID 40069619, 2025). "While current guidelines emphasize CD4+ count and viral suppression, persistent elevation of PD-1/PD-L1—even in virologically suppressed individuals—may signal residual immune dysfunction and increased risk for comorbidities." (PMID 40868140, 2025). "On the one hand, theoretical considerations suggest that a low CD4+ T cell count may be associated with chronic immune dysfunction, potentially increasing the risk of immune‐related toxicity from ICI." (PMID 41190419, 2025). "CD4 T cells are implicated in mediating immunodeficiency, particularly in the setting of HIV." (PMID 39188728, 2024). "In addition, increased IL-6 levels were significantly associated with low CD4+ T lymphocyte counts, which in fact has already been observed in baseline studies and is associated with immune dysfunction." (PMID 38992229, 2024). "For instance, the combination of high HIV RNA load and low CD4+ T-cell count may result in a more profound immune dysfunction and a higher risk of SSIs compared to either factor alone." (PMID 38988810, 2024). "This could result from rapid loss of CD4 cells, immune depletion or immunodeficiency, and susceptibility to opportunistic infection." (PMID 38223650, 2023). "The immune deficiency mechanism of anti-IFN-γ autoantibodies may include inhibition of the CD4 + T cells’ IFN-γ/pSTAT-1/Th1 pathway, ultimately leading to a severely compromised Th1 response." (PMID 37469600, 2023). "A diagnostic hallmark of this immunodeficiency is the reduced surface expression of CD4." (PMID 38112969, 2023). "However, these patients have a different pathophysiology underlying their immunodeficiency, and measures to assess disease control (such as CD4 count and viral load) were inconsistently reported in these studies." (PMID 37386535, 2023). "Indeed, immunodeficiency resulting from HIV infection is associated with depletion of key immune cells which participate in gut-brain axis interactions (mainly CD4+ T-cells) and persistent systemic inflammation." (PMID 37953826, 2023). "This may be due to the advanced WHO clinical stage and low CD4 count, which are indicators of severe immune deficiency are directly linked to undernutrition, especially protein and energy malnutrition." (PMID 36961844, 2023). "In progressor animals, experimental infection with FIV lentivirus resulted in a progressive and profound immunodeficiency characterized by an initial loss of peripheral CD4 T cells, eventually followed by loss of both CD8 T cell and CD21 lymphocyte subsets during the mid to late asymptomatic phase." (PMID 37632117, 2023). "Secondly, by activating tumor associated macrophages, myeloid-derived suppressive cells, Cd4+Foxp3+Treg cells or Th17 cells, inflammation could impair the immune response within tumors, promoting immune deficiency and cancer progression." (PMID 37063910, 2023). "In addition, LRA can generally cause some toxic side effects, such as over-activation of CD4+ T cells and immune disorders, which is also an urgent problem to be solved." (PMID 37108519, 2023). "Previous studies also indicated that the basic feature of RA is the body’s immune system disorders, in which autoreactive CD4 + T cells, pathogenic B cells, M1 macrophages, inflammatory cytokines, chemokines and autoantibodies abnormally increase in the body of RA patients." (PMID 36739468, 2023). "Previous studies have indicated that immune dysfunction may be involved in the pathogenic process of hypertension, while fewer studies have mentioned whether CD4+ T cells are involved in the association between dietary pattern and hypertension." (PMID 36678161, 2023).
Immunodeficiency (continued). "Abnormal CD4/CD8 ratio was associated with immune dysfunction in patients." (PMID 37759316, 2023). "Furthermore, low measles antibody concentration in HIV-infected children has been associated with severe immunodeficiency (< 25% CD4 + T cells, HIV VL ≥ 10,000 copies) in HIV-infected children, as well as to the short duration of antiretroviral treatment." (PMID 35562589, 2022). "Such CD4+ based immune deficiency often facilitates bacterial infection." (PMID 36059451, 2022). "It is reported that the pediatric population with CD4+ T lymphocyte levels lower than <15% (severe immunodeficiency) have a higher risk of developing severe forms, relapses, infection from multiresistant strains, adverse reactions to antituberculous drugs and higher mortality." (PMID 35271625, 2022). "Compared with healthy individuals, HD patients present with impaired immune function caused by immune disorders in both innate and adaptive immune systems, including altered monocyte phenotypes, reversal of the CD4 + /CD8 + ratio, and a significant decrease in naive T cells." (PMID 34436742, 2022). "It remains unclear whether HIV-associated immune dysfunction and inflammation are linked to severe COVID-19 disease outcomes or whether paradoxically a low CD4+ T cell count ameliorate disease severity." (PMID 36846557, 2022). "Of ADCs, KS was most closely associated with immunodeficiency, which median CD4 count was 52/μL." (PMID 34934097, 2021). "In patients with HIV infection, immunodeficiency significantly increases the risk of diseases caused by pathogens that expand as a consequence of the reduced level of CD4 T-lymphocytes, since pathogen load is usually controlled by humoral and cellular immune responses." (PMID 34959511, 2021). "This virus attacks CD4+ lymphocytes which lead to cell death and resultant immune deficiency." (PMID 34819855, 2021). "This suggests that, while CD8 activation does characterize the INR phenotype, CD4+ T cell immune alteration may also play a central role in INR-associated immune dysfunction." (PMID 34320023, 2021). "Consequently during malaria or TB infection, or immune deficiency with low CD4 counts, hepcidin levels are increased." (PMID 32107492, 2020). "HIV is a retrovirus that infects CD4+ T lymphocytes in human beings and causes immunodeficiency." (PMID 32566255, 2020). "Together, these results suggest that immune dysfunction might be a potential mechanism in the PD model and that CD4+ T cells are closely associated with PD pathogenesis and progression." (PMID 33568987, 2020). "Neonatal screening programs for detection of primary immune deficiencies show that in males, cord blood contains lower numbers of CD4+ T-lymphocytes, lower CD4/CD8 T-lymphocyte ratios, and higher CD8+ T-lymphocyte and NK cell counts than cord blood from females." (PMID 31921096, 2019). "The initial interest from hospital-based clinicians in the province in the pattern of presentation with very low CD4 counts was in response to ongoing morbidity from conditions such as cryptococcal meningitis, which are associated with advanced immunodeficiency." (PMID 29514233, 2018). "We found that HIV-related immune dysfunction (as represented by nadir CD4+ T cell count <200 cells/mm3) is associated with more than twofold greater odds of physician-adjudicated AF/AFL among HIV+ persons even after adjustment for demographics and CVD risk factors." (PMID 29558525, 2018). "In light of our findings, it is plausible that HIV-related immune dysfunction (as reflected in low nadir CD4+ T cell count) and inflammation increase susceptibility to AF/AFL, but longitudinal studies incorporating biomarker data would be instrumental in further elucidating these mechanisms." (PMID 29558525, 2018). "Lower CD4+ T cell counts account for immuno-deficiency and uncontrolled viral loads, and may also contribute to increased HIV infection in the late group compared to the other groups." (PMID 29467460, 2018).
Immunodeficiency (continued). "On one side, HIV-infected patients may experience various levels of immune deficiency, because of lower CD4 cell count and immune dysregulation, malignancies or rheumatologic diseases." (PMID 28249574, 2017). "Local opinion leaders in South Africa continue to stress that baseline CD4 would still be required to assess immune deficiency, life threatening co-infections (such as Cryptococcal disease) and enable fast-tracking severely immune suppressed patients onto ART, hence the basis of this report." (PMID 28829788, 2017). "However, even 1 year post-therapy, the immune system maintains an unusually Th2-biased composition, potentially underlying continued immunodeficiency in the presence of higher CD4+ T-cell counts." (PMID 27819062, 2016). "In spite of the theoretical concern regarding the association of PNP inhibition and immunodeficiency, we showed that in normal healthy mice, IH stimulates the proliferation of CD4+ and CD8+-T and CD19+-B cells after direct contact or systemic previous treatment." (PMID 26701750, 2015). "As previously reported by others, HIV-related immunodeficiency, which is associated with low CD4 counts, may lead to a weak anti-HCV Ab response." (PMID 25617896, 2015). "The total patient group was severely tryptophan depleted compared to the controls (24.36 ± 4.14 μmol/l vs. 43.57 ± 11.85 μmol/l; p < 0.0001) and the degree of tryptophan depletion correlated with the degree of immune deficiency (tryptophan vs. CD4: r = 0.341; p = 0.004)." (PMID 26285873, 2015). "They suggested that immune deficiency, such as those caused by CD4+ T cell deficiency or impaired anticryptococcal activity of monocytes would reduce the protective cytokine levels, which possibly contribute to the low clearance of C. neoformans in PC patients." (PMID 26637129, 2015). "Finally, immunodeficiency appeared to be strongly linked to malnutrition at time of treatment initiation, but the predictive value of baseline CD4 was somewhat weaker in multilevel modeling." (PMID 26825478, 2015). "However, most studies to date have focused on single/double measurements of immune dysfunction, while the identification of pathological CD4+ T cell clusters that is highly associated to a specific biomarker for HIV disease remain less studied." (PMID 26402620, 2015). "R5-tropic viruses associated with early stages of infection are preferentially transmitted, while non-R5 HIV-1 tropism has been associated with severe immunodeficiency and lower lymphocyte CD4 nadir and may reflect delayed HIV diagnosis." (PMID 25397437, 2014). "Despite ART, these patients had profound immune deficiency as seen from their CD4 cell level." (PMID 24854196, 2014). "Furthermore, the immune dysfunction that is associated with HIV infection is not limited to CD4+ T lymphocytes." (PMID 24995137, 2014). "The finding that HIV is confined to CD4+ leukocytes and is cytopathic for CD4+ T cells established the hypothesis that HIV causes immune deficiency by directly killing CD4+ T cells and impeding CD4+ T-cell renewal." (PMID 24133492, 2013). "Human studies of primary immune deficiencies strongly indicate that CD4 T cells may be even more important than CD8 T cells in the control of herpes virus infections." (PMID 23717308, 2013). "Moreover, as the lentiviruses of cats and humans have evolved two distinct strategies to selectively target infection of CD4+ helper T cells, inter-species comparisons offer a unique opportunity to discern what makes immunodeficiency-causing lentiviruses tick." (PMID 23992667, 2013). "Severe immunodeficiency (manifest as a low CD4 count) may be associated with later features of the senescence pathway, ultimately leading to cell cycle arrest and cell loss." (PMID 23460854, 2013). "Immunodeficiency associated BL is more commonly seen with human immunodeficiency virus (HIV) infection than other forms of immunodeficiency though its incidence is lowest in patients with a CD4 count <50 cells/mL." (PMID 22190945, 2012).
Immunodeficiency (continued). "The association of lower CD4+ T-lymphocyte (CD4) counts with higher risk of MRSA infection suggests that the MRSA infection risk may be increased by immunodeficiency and raises concern for higher risk of invasive MRSA infection." (PMID 23008761, 2012). "HIV infection causes depletion of CD4-positive lymphocytes with consequent immunodeficiency." (PMID 22991655, 2012). "In contrast, the response could be altered in advance immune-deficiency state, as indicated by low CD4+ T-cell counts." (PMID 22550534, 2012). "Similarly, children with absolute CD4 count below the threshold for severe immunodeficiency were 2.24 (95% CI: 1.07, 4.69) times at risk of death." (PMID 23043325, 2012). "Similarly, low haemoglobin level and absolute CD4 count below the threshold for severe immunodeficiency were significantly and independently associated with mortality of HIV-positive children." (PMID 23043325, 2012). "To determine whether changes in sphingolipid composition are associated with age-related immune dysfunction, we analyzed the core sphingolipidome (i.e., all of the metabolites through the first headgroup additions) of young and aged CD4+ T cells." (PMID 23110086, 2012). "Loss of antiviral IFNγ production by CD4+ T cells, as well as loss of direct cytotoxic activity against infected cells, contribute to immunodeficiency, but more important may be the loss of CD4+ T cell helper activity." (PMID 21943070, 2011). "M.tb re-activation may occur in the context of only moderate immunodeficiency, but the risk of TB is generally inversely related to the CD4+ T cell count and is greatest when the CD4+ T cell count dips below 200 cells/mm3." (PMID 21209722, 2010). "An association between liver cancer risk and low CD4+ cell count in the year preceding liver cancer has recently been reported, suggesting that immunodeficiency may contribute to the liver cancer excess in PWHA." (PMID 19223894, 2009). "Only patients with advanced immunodeficiency were included and the restricted cohort composition may have diminished the association between mortality and risk factors such as CD4 cell count." (PMID 17509133, 2007). "The enumeration of CD4+ T-lymphocytes by flow cytometry is used routinely in the clinical management of HIV-infected individuals to monitor the severity of immunodeficiency caused by HIV, and this acts as a basis for commencing HAART and prophylaxis for Pneumocystis carinii pneumonia." (PMID 18036256, 2007). "Moreover, advanced pre-treatment immunodeficiency is also reported to be associated with diminished capacity for restoration of CD4 cell counts and CD4 cell functional responses during ART." (PMID 16551345, 2006). "The main hypotheses are that HBV is responsible for chronic immunological stimulation, while HIV antigens act like superantigens and stimulate B cell proliferation determining immunoglobulins production; on the other hand, HIV infection causes CD4+ T cell depletion, which induces immunodeficiency." (PMID 40182311, 2025). "Therefore, under conditions of chronic HBV infection, characterized by many inflammatory cytokines (a cytokine storm) in HBV-ACLF, CD4+ T cells are more susceptible to immune dysfunction than CD8+ T cells and are more vulnerable to the effects of the inner inhibitory microenvironment (such as BTLA)." (PMID 38418488, 2024). "Although high CD4 cells counts have been associated with higher vitamin D levels, while low vitamin D levels is linked to immune dysfunction that also influence the expression of inflammatory markers, we could not establish this outcome owing to the scope of our study." (PMID 37790569, 2023). "Moreover, it is unknown whether CD4 T cell immune deficiency can modify vascular reactivity of ICA in the PP period." (PMID 34220551, 2021).
Immunodeficiency (continued). "In addition, it has been reported that in PLWH, gut microbiota alterations are closely associated with immune dysfunction, and lower bacterial α-diversity correlates with lower CD4+ T-cell counts and higher markers of microbial translocation and monocyte activation." (PMID 35069530, 2021). "A plausible explanation associations with NAEs is that low CD4/CD8 ratio could be a marker of ongoing immune dysfunction among prolonged virologically suppressed HIV patients on stable cART since immune activation is been associated with clinical events and mortality in PLHIV." (PMID 30261902, 2018). "Furthermore, we set out to determine whether CD4+ T cells with specific pathological phenotypes were elevated and associated with immunodeficiency in aviremic HIV-2 infection." (PMID 27525551, 2016). "Together, these observations have gradually shifted the paradigm from the classical hypothesis that viral cytopathicity is the primary driver of CD4+ T-cell depletion and immune deficiency, to the hypothesis that chronic immune activation is the cause of T-cell depletion and immune deficiency." (PMID 24133492, 2013). "Experiments using SHIV infection in rhesus macaques indicate that the difference between immunodeficiency and prolonged survival may be programmed early – the outcome could be traced back to the degree of severity of viremia and CD4+ T cell loss during the acute phase." (PMID 21359149, 2011). "The loss of CD4+ T cells could induce a state of immunodeficiency in older individuals." (PMID 19557183, 2009). "Stratified analyses indicated consistent associations across most subgroups, while logLAP showed limited associations in children aged 0-7 years and those with severe immune dysfunction (CD4+/CD8+ T cell counts below the reference range)." (PMID 42058714, 2026). "The TyG-CD4 stratification model proposed in this study is designed to address this heterogeneity by integrating two key dimensions of host vulnerability: immune dysfunction (CD4 count) and metabolic dysregulation (TyG index)." (PMID 41601726, 2026). "This form occurs at a degree of immunodeficiency with an average CD4 lymphocyte count greater than 200/mm3." (PMID 41209966, 2025). "Notably, patients with suboptimal CD4+ T-cell recovery (persistent counts <200 cells/μL) demonstrated greater susceptibility to R-S cell development even during antiretroviral therapy, suggesting the critical role of sustained immunodeficiency in lymphomagenesis." (PMID 40969752, 2025). "There are potential biomarkers emerging for immunodeficiency, chronic inflammation (CD4+, CD8+, T cells, B cells, IgA, IgG2, hyper IgM, IL-6 and IL-8) and steroid therapy use." (PMID 39812834, 2025). "FIV primarily infects CD4+ T-helper cells, B lymphocytes, and macrophages, leading to progressive immunodeficiency." (PMID 41471183, 2025). "HIV directly destroys the “command center” of the immune system (CD4+ T cells), leading to global immunodeficiency." (PMID 40766314, 2025). "In human immunodeficiency, an increased CD4/CD8 ratio in CBC is considered an improvement in immunity." (PMID 40422255, 2025). "However, the difference in the antiviral immune response activation can may explain this phenomenon: sooty mangabeys infected by SIVsmm have high viral loads but do not show chronic immune activation and inflammation leading to a progressive CD4 + T cell loss and immunodeficiency." (PMID 40884399, 2025). "FIV is a lymphotropic virus, formerly designated as T-lymphotropic lentivirus, and it preferentially replicates within CD4+ T lymphocytes, leading to their depletion and dysfunction, the primary mechanism underlying FIV-induced immunodeficiency." (PMID 40877940, 2025). "In contrast, our patient was diagnosed with thymoma at the age of 46, with immunodeficiency features such as low immunoglobulin levels and reduced CD4 and NK cell counts discovered about a year later." (PMID 40630374, 2025).